F5 (coagulation factor V)
Description:
Central regulator of hemostasis. It serves as a critical cofactor for the prothrombinase activity of factor Xa that results in the activation of prothrombin to thrombin.
Synonyms: fV; FVL; PCCF; RPRGL1; THPH2
Tractability: Small molecule: a structure with a bound ligand is known; a high-quality ligand is known. Antibody: its Gene Ontology location is reachable by antibodies, with high confidence; UniProt places it where antibodies can reach, with medium confidence; UniProt predicts a signal peptide or a membrane-spanning region. PROTAC: its protein half-life has been measured; a small molecule that binds it is known. Other modalities: an approved drug acts on it.
Target class: Secreted protein
Safety:
Unwanted effects reported when the protein is acted on. In parentheses: how it was acted on, where the effect was seen, and who reports it.
thrombosis (source: ClinPGx)
Gene: Protein-coding gene on chromosome 1 (169,511,951 to 169,586,588, reverse strand). Ensembl gene ENSG00000198734.
Subcellular location: Secreted
Subcellular location (Human Protein Atlas): Golgi apparatus; Predicted to be secreted
Pathways (Reactome):
Hemostasis: Amplification and propagation of coagulation cascade; Initiation of coagulation cascade; Platelet degranulation; Regulation of clotting cascade
Disease: Defective cleavage of FV variant at R334; Defective cleavage of FV variant at a.a.534
Metabolism of proteins: Post-translational protein phosphorylation; Regulation of Insulin-like Growth Factor (IGF) transport and uptake by Insulin-like Growth Factor Binding Proteins (IGFBPs)
Vesicle-mediated transport: COPII-mediated vesicle transport; Cargo concentration in the ER
Gene Ontology:
Molecular function: protein binding; copper ion binding
Biological process: blood circulation; blood coagulation; response to vitamin K
Cellular component: extracellular vesicle; membrane; COPII-coated ER to Golgi transport vesicle; endoplasmic reticulum lumen; endoplasmic reticulum-Golgi intermediate compartment membrane; extracellular region; plasma membrane; platelet alpha granule; platelet alpha granule lumen
Genetic constraint (gnomAD): Loss-of-function variants: 130 observed, 213.58 expected, observed/expected ratio (o/e) 0.61, 90% interval 0.53 to 0.7. The upper end of that interval is the gene's LOEUF score, 0.7, which puts it in group 2 of 6, group 1 being the genes least tolerant of losing a copy. Missense variants: 2,352 observed, 2,752.3 expected, observed/expected ratio (o/e) 0.85, 90% interval 0.82 to 0.88. Synonymous variants: 902 observed, 959.69 expected, observed/expected ratio (o/e) 0.94, 90% interval 0.89 to 0.99.
Gene-disease validity (ClinGen):
ClinGen rates the evidence that F5 causes each of these diseases.
congenital factor V deficiency (autosomal recessive): Definitive. Congenital factor V deficiency is an inherited bleeding disorder due to reduced plasma levels of factor V (FV) and characterized by mild to severe bleeding symptoms.
thrombophilia due to activated protein C resistance (autosomal dominant): Definitive. A hemostatic disorder characterized by a poor anticoagulant response to activated protein C (APC).
Homologues: Orthologues: chimpanzee F5 (99% identical), macaque F5 (91% identical), dog F5 (77% identical), pig F5 (76% identical), rabbit F5 (72% identical), mouse F5 (68% identical), rat F5 (68% identical), guinea pig F5 (67% identical), tropical clawed frog f5 (39% identical), zebrafish f5 (34% identical). Paralogues in human: F8 (29% identical), HEPH (17% identical), HEPHL1 (17% identical), CP (16% identical), CUBN (8% identical), CNTNAP2 (8% identical), NRXN2 (8% identical), NRXN3 (7% identical), NRXN1 (7% identical), CNTNAP5 (7% identical), CNTNAP4 (7% identical), CNTNAP3B (7% identical), and 23 more.
Diseases named in the same sentence as F5 in open-access papers:
F5 is named in the same sentence as 292 diseases in open-access papers, as found by Europe PMC text mining. Sharing a sentence is not in itself a finding about the gene and the disease. The quoted sentences say what the papers report.
thrombophilia (369 papers, 2005 to 2026). A condition characterized by an abnormally high level of thrombi. "Factor V Leiden results from a mutation in the F5 gene that encodes factor V of the coagulation cascade and is the most common thrombophilia." (PMID 39184648, 2024). "The authors confirmed the association between candidate gene Factor V Leiden (F5), also involved in coagulation, and fetal loss, but pointed out that relationship between thrombophilias and pregnancy loss varies according to ethnicity and loss type." (PMID 35462723, 2021). "Inherited thrombophilia is usually due to mutations in the coagulation factor V (factor V Leiden) and prothrombin (prothrombin G20210A) genes." (PMID 29851836, 2018). "The F5 gene has many known mutations causing different blood coagulation disorders like factor V deficiency and factor V Leiden thrombophilia." (PMID 27508393, 2016). "One variant in the gene F5 (Entrez Gene ID 2153), encoding the coagulation factor V, confers activated protein C resistance and increased risk for thrombophilia." (PMID 21935354, 2011). "Factor V Leiden mutation in the F5 gene causes Factor V Leiden thrombophilia." (PMID 37629250, 2023). "Factor V Leiden mutation in the F5 gene causing factor V Leiden thrombophilia (rs6025(A))." (PMID 34356593, 2021). "Sanger sequencing revealed three other patients with either the thrombophilia predisposing regulatory prothrombin gene F2 variant c.20210G>A, the known loss-of-function variant in the factor V-Leiden gene F5 c.1691G>A p.Arg506Glu or both variants together in a heterozygous state." (PMID 32397294, 2020). "Beside G1691A, factor V Leiden, several studies have shown that A4070G polymorphism also could cause thrombophilia and play a role in coagulation factor V deficiency, but factor V Leiden (G1691A) is well known as a risk factor." (PMID 27326418, 2016). "The most common inherited thrombophilias are the single nucleotide polymorphisms Factor V Leiden, which renders coagulation factor V resistant to the anticoagulant effects of activated protein C, and Prothrombin G20210A, which leads to elevated plasma prothrombin levels." (PMID 17711595, 2007). "In addition, several coagulation factors such as Factor 5 (F5, coagulation factor V; causative gene in Factor V Leiden thrombophilia), F8 and F12, which are part of the Intrinsic Prothrombin Activation Pathway, were up-regulated at 24 h in IS participants with poor 90d outcomes." (PMID 36691064, 2023). "FV Leiden thrombophilia is an autosomal dominant thrombophilic coagulopathy characterized by the presence of a mutation at the binding site to APC in the F5 gene, specifically at the residue of arginine 506, a cleavage site for APC." (PMID 35955419, 2022).
thrombosis (157 papers, 2005 to 2025). "After reviewing the procoagulant and anticoagulant functions of FV, we discuss the mechanisms by which F5 gene mutations can alter their delicate balance and thus increase the risk of bleeding or venous thrombosis." (PMID 38404937, 2024). "Resistance to aPC occurs due to a decreased inhibition of activated coagulation factor V (FVa) by aPC and is an important risk factor for venous thrombosis." (PMID 37057100, 2023). "Factor V Leiden (F5 R506Q) and prothrombin gene mutation (F2 G20210A) have been associated with thrombosis in PV and ET." (PMID 30426472, 2019). "A well-established genetic predisposition to venous thrombosis that occurs in approximately 5% of Caucasian populations is a single-point mutation in the gene encoding coagulation factor V (G1691A) or Factor V Leiden (FVL)." (PMID 29372059, 2018). "Here, we review the procoagulant and anticoagulant functions of FV and the manifold mechanisms by which F5 gene mutations may affect the balance between these opposite functions and thereby predispose individuals to bleeding or venous thrombosis." (PMID 38404937, 2024). "The FVL (F5 gene mutation 1691G > A (rs6025)) results in an altered variant of factor V, which enhance resistance to inactivation by protein C and hypercoagulable state with a five-to-tenfold risk of thrombosis in heterozygote and an 80-fold risk in homozygote individuals 5,6." (PMID 38974294, 2023). "For example, the identification of F5 p.Arg534Gln (factor V Leiden) gene has been identified as an overlapping locus of focus for both VVs and deep venous thrombosis." (PMID 41391741, 2025). "The F5 rs4524 variant (R534Q) is known to modulate factor V cofactor activity and has been linked to a decreased risk of thrombosis in individuals without the FVL mutation." (PMID 41440514, 2025). "The purpose of this study was to explore the negative influence coagulation factor V (FV) 1691G>A polymorphism had on the risk and prognosis of lower extremity deep venous thrombosis (LDVT) in Chinese Han population." (PMID 29851809, 2018). "But for patients with thrombosis, detection of MPNs and its related genes such as JAK2V617F, coagulation factor V Leiden, thrombin G20210A, PNH, MTHFR gene, protein C and S, and other factors is reasonable." (PMID 36567373, 2023). "Therefore, tests of FVL, coagulation factor VIII, antithrombin, and protein C are only recommended for patients with a thrombosis family history and who suffered from unexplained FRSA." (PMID 28798930, 2017).
coagulation disorders (46 papers, 2011 to 2026). "Coagulation disorders and thrombocytopenia, TORCH infections, selected genetic abnormalities (factor V Leiden (F5) 1601G > A polymorphism and MTHFR 677C > T; 1298A > C polymorphisms), and metabolic disorders were also excluded." (PMID 27392444, 2016).
Stroke (46 papers, 2007 to 2025). Sudden impairment of blood flow to a part of the brain due to occlusion or rupture of an artery to the brain. "F5 has been consistently implicated in stroke, while F12's involvement has recently been elucidated." (PMID 25036109, 2014). "If replicated, this would be consistent with modest risk increase for stroke that other variants associated to circulating D-dimer levels, such as reported for variants in coagulation Factor V, Factor III and FGA." (PMID 25078778, 2014). "The results showed that 6 genes filtered with optimal lambda value were identified as diagnostic characteristic genes in stroke, namely, HAS3, VIM, ZFP36L2, CPQ, F5, and PIK3CG." (PMID 38649659, 2024). "After taking the intersection of SCFA metabolism-related genes and the co-expression WGCNA modules of stroke, 10 SCFA-related hub genes were obtained, and 6 of them showed high diagnostic efficacy through LASSO regression and ROC analysis, including HAS3, VIM, ZFP36L2, CPQ, F5, and PIK3CG." (PMID 38649659, 2024).
bleeding disorder (20 papers, 2011 to 2025). "Autoimmune acquired factor V deficiency (AiFVD) is a rare bleeding disorder characterized by the presence of inhibitors against coagulation factor V (factor V)." (PMID 40821335, 2025). "For the remainder of this article, I will focus on work from my laboratory over the past 20 years that began with the study of another very rare inherited human bleeding disorder, combined deficiency of coagulation factor V (FV) and FVIII (F5F8D)." (PMID 39545422, 2024). "An apparently unrelated family from Indiana was found to segregate the same F5 mutation identified in the East Texas bleeding disorder, which acts by strengthening the natural donor splice site for FV splicing." (PMID 38404937, 2024). "Hereditary FVD caused by defects in the F5 gene is the most common FV-related bleeding disorder." (PMID 38115300, 2023). "East Texas bleeding disorder is caused by a rare variant at A2440G mutation in exon 13, predicting a S756G mutation in the B domain of FV, which causes upregulation of an alternatively spliced F5 transcript that results in a 250kDa isoform known as FV-short." (PMID 35224470, 2022). "This is upheld by the elevated levels of TFPIα in individuals that have F5 gene variations that increase the efficiency of the splicing events that generate FV-short such as those with East Texas bleeding disorder, FV-Amsterdam and FV-Atlanta." (PMID 39259668, 2024). "Genetic studies identified mutations in LMAN1 as the cause for the combined deficiency of coagulation factor V (FV) and factor VIII (FVIII) (F5F8D), which is an autosomal recessive bleeding disorder with both FV and FVIII in 5–30% of normal." (PMID 37334845, 2023).
ischemic stroke (17 papers, 2009 to 2025). A stroke disorder caused by obstruction of blood flow to the brain, due to thrombotic (local blood clot formation) or embolic (due to a blood clot or other material traveling from another site) event. "However, many genes associated with ischemic stroke are not affected by tPA including BCL6, F5, and LY96 which were previously found to be predictive of ischemic stroke in humans." (PMID 20406488, 2010).
Thromboembolism (16 papers, 2005 to 2026). The formation of a blood clot inside a blood vessel that subsequently travels through the blood stream from the site where it formed to another location in the body, generally leading to vascular occlusion at the distant site. "One of the disorders associated with this variant is thromboembolism whose genetic risk is increased also by p.Gln534Arg in coagulation factor V (factor V Leiden variant), which is also reported in gnomAD and quite common (allele frequency of 9.81E−01)." (PMID 33260935, 2020).
COVID-19 (14 papers, 2021 to 2025). A disease caused by infection with severe acute respiratory syndrome coronavirus 2. "Therefore, B4GALT5, CRISPLD2 and F5 may be potent targets for the treatment of COVID-19-associated IS." (PMID 37606960, 2023). "We then analyzed the mRNA expression of 9 genes, and 3 genes (B4GALT5, CRISPLD2, F5) were found up-regulated in both COVID-19 and IS (p < 0.001)." (PMID 37606960, 2023). "What’s more, a recent study suggested coagulation factor V as an immune inhibitor that is expressed at increased levels in leukocytes of patients with severe COVID-19." (PMID 36094909, 2022). "Finally, three genes associated with immunity (B4GALT5, CRISPLD2, F5) and two genes associated with ferroptosis (ACSL1, CREB5) were identified up-regulated in COVID-19-related IS." (PMID 37606960, 2023). "Characteristic biomarkers showed high diagnostic efficacy in distinguishing COVID-19-related IS from control samples, with an AUC of 0.984 (95% CI 0.950–1,000) for B4GALT5, 0.966 (95% CI 0.914–0.998) for CRISPLD2, and 0.991 (95% CI 0.966 to 1.000) for F5." (PMID 37606960, 2023). "Likewise, in bioinformatic analysis, F5 was identified as a gene shared among COVID-19 comorbidities (kidney disease, liver disease, diabetes, lung disease, and cardiovascular disease)." (PMID 35453794, 2022).
breast carcinoma (13 papers, 2014 to 2025). "We have reported that FV was elevated in breast cancer tumors, and that high F5 mRNA levels were associated with improved overall survival and treatment response to chemotherapy, as well as induced apoptosis and reduced proliferation in breast cancer cells." (PMID 40725392, 2025). "F5 is an essential regulator in the blood coagulation cascade, and F5 expression has been linked to increased cancer risk and tumor aggressiveness in breast cancer, colorectal cancer, and gastric cancer." (PMID 36555753, 2022). "On the other side, high expression of coagulation factor 5 (F5) was found to be associated with improved overall survival of patients with breast cancers." (PMID 35626004, 2022). "We aimed to investigate whether the F5 variants FV Leiden (F5 rs6025) and F5 rs6028 influenced FV expression, coagulant activity, and apoptosis in breast cancer cells." (PMID 40725392, 2025). "FV gene (F5) expression and F5 variants have been linked to breast cancer progression." (PMID 40725392, 2025). "The F5 expression has been associated with tumor aggressiveness and has been identified as an immunological marker for the cancer-inflammation-thrombosis circuit in breast cancer." (PMID 38555418, 2024). "F5 was recently found to be capable of being expressed in extravascular tissues, including breast cancer cells and tumor-permeable immune cells." (PMID 35836573, 2022). "Interestingly, our study shows that the high expression of F5 is correlated with a poor OS in GC, and this contradicts a previous study in which high F5 expression improved OS for the basal type of tumours in breast cancer according to the KM-plotter website." (PMID 32190689, 2020). "The F5 variants might therefore enhance the tumor suppressor function of FV in breast cancer." (PMID 40725392, 2025). "F5 also demonstrated strong similarity to published myCAF signatures, including Elyada myCAF and LRRC15+ fibroblasts from pancreatic cancer, pan-cancer C10_COMP+ CAF, ECM/TGFβ myCAF from breast cancer and Liu myCAF from PCa." (PMID 41378308, 2025).
diabetes (13 papers, 2009 to 2025). "We thus found four hub genes (App, F5, Fgg, and Gas6) that were closely related to vascular regulation and diabetes." (PMID 34531764, 2021).
Obesity (11 papers, 2008 to 2025). Accumulation of substantial excess body fat. "Notably, CPN2 (carboxypeptidase N Subunit 2), F5 (coagulation factor V), ECM1 (extracellular matrix protein 1), KNG1 (kininogen 1), FN1 (fibronectin 1), and GPLD1 (glycosylphosphatidylinositol-specific phospholipase D1) were found to be elevated in both human and mouse sEVs under obesity conditions." (PMID 38402239, 2024).
factor V deficiency (10 papers, 2011 to 2026). A coagulation disorder characterized by the partial or complete absence of factor V activity in the blood. "Acquired factor V deficiency (AFVD) is a rare disease characterized by a relative deficiency of coagulation factor V (FV) due to the presence of internal FV inhibitors." (PMID 42311902, 2026). "In patients with Owren’s parahemophilia (with congenital factor V deficiency), the existence of functional platelet-derived coagulation factor V is thought to support enough thrombin generation to prevent severe bleeding in patients with virtually undetectable plasma factor V." (PMID 36361561, 2022).
Sepsis (10 papers, 2008 to 2025). Sepsis is defined as life-threatening organ dysfunction caused by a dysregulated host response to infection. "The impact of factor V Leiden (FVL), a procoagulant variant of coagulation factor V, in sepsis mortality is also worth discussing." (PMID 25943883, 2015). "Genes such as CSF3, ELANE, F5, and GALT exhibited significant differential expression between sepsis patients and controls." (PMID 41194984, 2025).
Arterial thrombosis (9 papers, 2008 to 2025). The formation of a blood clot inside an artery. "Platelet-derived Factor V (F5) was found to be a critical mediator of arterial thrombosis in mice and CAD patients show significantly higher levels of plasma FN1 as compared to healthy subjects, with platelet FN1 levels correlating with severity of disease." (PMID 32671099, 2020).
Hypertension (9 papers, 2013 to 2025). The presence of chronic increased pressure in the systemic arterial system. "Of particular interest are the SNPs within the NOS3 (endothelial nitric oxide synthase), F5 (Leiden factor), TNFSF4 (cytokine pathway), and CDKN2B-AS1 (cell cycle regulation) genes, which may play a key role in the development of vascular dysfunction and hypertension in this pathology." (PMID 40507612, 2025).